CUL5 (cullin 5)
Diseases named in the same sentence as CUL5 in open-access papers (continued):
Sharing a sentence is not in itself a finding about the gene and the disease.
asthma (3 papers, 2022 to 2025). "To explore the potential pathophysiological role of CUL5 in AMs during asthma exacerbations, we generated myeloid-specific Cul5-deficient mice (LysMCreCul5fl/fl) by breeding Cul5-floxed mice (Cul5fl/fl) with Lysozyme M-Cre mice (LysMCre)." (PMID 38177117, 2024). "By contrast, CUL5 deficiency mitigates neutrophilic lung inflammation and asthma exacerbations by augmenting IFN-β production." (PMID 38177117, 2024). "The expression of IFN-β and the interferon-associated genes was significantly increased in CUL5 deficient macrophages of influenza or dsRNA-induced asthma exacerbation mice in vivo, and Poly(I:C)-stimulated BMDMs or PMA-induced THP-1 macrophages in vitro." (PMID 38177117, 2024). "Neutrophilic cytokines, including Tgfb, Tnfa, Cxcl15, Elane, and Mmp9, also showed significantly reduced expression in Poly(I:C)-induced asthma exacerbation mice after CUL5 deficiency." (PMID 38177117, 2024). "Supporting this, mice that lack Cul5 in T cells are more susceptible to allergen-induced airways remodeling and asthma." (PMID 35589717, 2022). "Taken together, these results indicated that Cul5 limits the frequencies and numbers of Th2 and Th9 cells, prevents lung remodeling and other pathologic features associated with asthma." (PMID 35589717, 2022). "CUL5-deficient mice presented less severe asthma pathogenesis than control mice." (PMID 38177117, 2024). "Next, we used a double-stranded RNA (dsRNA, Poly(I:C))-induced asthma exacerbations model to further examine the role of CUL5 in asthma exacerbations." (PMID 38177117, 2024). "Taken together, these results highlight the importance of CUL5 in influenza-induced asthma exacerbations." (PMID 38177117, 2024). "Our findings propose an important function for CUL5 in virus-induced asthma exacerbations, indicating CUL5 as a target for asthma exacerbations treatment." (PMID 38177117, 2024). "Collectively, these results indicate that CUL5 is upregulated in AMs of mice with influenza-induced asthma exacerbations." (PMID 38177117, 2024). "Collectively, these data demonstrate the essential role of CUL5 in promoting experimental asthma exacerbations, probably by regulating airway neutrophilic inflammation." (PMID 38177117, 2024). "Our results thus suggest that, in mouse models, pre-existing allergic injury induces CUL5 expression, impairing antiviral immunity and promoting neutrophilic inflammation for asthma exacerbations." (PMID 38177117, 2024). "Collectively, our data indicate that CUL5 promotes virus-induced asthma exacerbations and neutrophil migration by suppressing IFN-β expression." (PMID 38177117, 2024). "Given the inhibitory effect of CUL5 on antiviral immunity, we attempted to determine the upstream signaling of CUL5 in asthma." (PMID 38177117, 2024). "The epithelial alarmin TSLP induces the expression of CUL5, which then interacts with and degrades OGT via K48-linked ubiquitination, inhibiting MAVS O-GlcNAcylation and IFN-β production, and eventually inducing asthma exacerbations." (PMID 38177117, 2024). "Targeting of the CUL5/IFN-β signaling axis may thereby serve as a possible therapy for treating asthma exacerbations." (PMID 38177117, 2024). "Here using mouse models we find that Cullin5 (CUL5), a key component of Cullin-RING E3 ubiquitin ligase 5, is upregulated and associated with increased neutrophil count and influenza-induced exacerbations of house dust mite-induced asthma." (PMID 38177117, 2024). "In our study, we observed an upregulation of CUL5 in AMs with virus-induced asthma exacerbations." (PMID 38177117, 2024). "Therefore, our data indicates that CUL5 is a potential therapeutic target for virus-induced asthma exacerbations, and further research is required to validate its role in human and investigate the clinical application of IFN-β in treating asthma exacerbations." (PMID 38177117, 2024). "In summary, our data demonstrate that CUL5 is a modulator of virus-induced asthma exacerbations." (PMID 38177117, 2024).
asthma (continued). "Thus, our study suggests IFN-β and CUL5 as promising therapeutic targets in acute asthma exacerbations." (PMID 38177117, 2024). "Additionally, CUL5 deficiency reduced capillary rupture, total protein content and total cell count in BALF, and serum IgE levels in mice with dsRNA-induced asthma exacerbations." (PMID 38177117, 2024). "Notably, the upregulated CUL5 aggravates asthma exacerbations and mechanistically promotes neutrophil accumulation by inhibiting antiviral immunity and type 1 interferon production." (PMID 38177117, 2024). "To determine the mechanism by which CUL5 regulates virus-induced asthma exacerbations, we performed transcriptome RNA-seq analysis to assess the difference in AMs of influenza-induced LysMCreCul5fl/fl and Cul5fl/fl asthma exacerbation mice." (PMID 38177117, 2024). "To date, no genetic polymorphism studies have implicated Cul5 or CIS in human allergic diseases such as asthma, although it has been implicated in autoimmune and infectious disease." (PMID 35589717, 2022). "Given the role of OGT-mediated MAVS O-GlcNAcylation in the CUL5-mediated inhibition of antiviral immunity in vitro, we investigated the role of OGT in CUL5-mediated asthma exacerbations in vivo." (PMID 38177117, 2024). "Here, we found that during asthma, the epithelial alarmin TSLP induces the expression of CUL5, which acts as a master regulator of IFN-β production in AMs, thereby controlling neutrophil accumulation and its associated effects in the airways." (PMID 38177117, 2024). "However, the role of CUL5 in virus-induced asthma exacerbations remains unknown." (PMID 38177117, 2024). "In the absence of Cul5, CD4+ T cells became overly sensitive to IL-4 which contributed to asthma pathogenesis." (PMID 35589717, 2022).
breast tumor (3 papers, 2005 to 2015). "Similarly, underexpression of CUL5 linked to genetic loss events has been documented in breast tumors." (PMID 25298778, 2014). "Fay and colleagues have found a decrease level of CUL5 in human breast tumor tissue supporting its potential role in breast tumorigenesis." (PMID 25929337, 2015).
endometrial carcinoma (2 papers, 2018 to 2022). A malignant tumor arising from the epithelium that lines the cavity of the uterine body. "In concordance, CUL5 overexpression led to significantly slower growth in some endometrial cancer cells." (PMID 29594129, 2018). "Similarly, CUL5 is significantly decreased in endometrial cancers with the most aggressive type of cancer displaying the highest CUL5 reduction." (PMID 29594129, 2018).
glioblastoma (2 papers, 2016 to 2021). The most malignant astrocytic tumor (WHO grade IV). "Clathrin-coated pits are absent from the ventral surface of the leading edge of motile glioblastoma cells and were absent from the long leading lamellipodium of Cul5-deficient MCF10A cells." (PMID 27656905, 2016).
liver cancer (2 papers, 2018 to 2025). An epithelial or non-epithelial malignant neoplasm that arises from the liver. "CUL5 is also a direct target of miR-7 in liver cancer through direct miR-7 binding to the CUL5 3′UTR." (PMID 29594129, 2018).
neuroblastoma (2 papers, 2009 to 2025). Neuroblastoma (NB) is the most common solid, extracranial childhood tumor. "As such, our finding suggests that Cul5-Wsb2 inhibitors may adversely affect growth of Neuroblastomas irrespective of the BCL2 family member by causing strong up-regulation of Bim." (PMID 40832228, 2025). "Based on this, the possibility that in neuroblastoma cells an E3 ligase other than AIP4, possibly Cul-5, mediates modification of CXCR4 is intriguing." (PMID 20028517, 2009).
ovarian carcinoma (2 papers, 2021 to 2024). A malignant neoplasm originating from the surface ovarian epithelium. "In multiple cancer types, including ovarian cancer, leukemia, and melanoma, high cytotoxic T cell score is associated with an overall survival benefit only when CUL5 expression is low, while high CUL5 expression abolishes and even reverses the beneficial effects of infiltrating cytotoxic T cells." (PMID 38242867, 2024).
small cell lung carcinoma (2 papers, 2021 to 2023). Small cell lung cancer (SCLC) is a highly aggressive malignant neoplasm, accounting for 10-15% of lung cancer cases, characterized byrapid growth, and early metastasis. "In small-cell lung cancer, low expression levels of cullin 5 (CUL5) and suppressor of cytokine signaling 3 (SOCS3) correlate with a highly metastatic phenotype and poor prognosis." (PMID 34131655, 2021).
thyroid cancer (2 papers, 2021 to 2022). "In our study, we found that CUL5 inhibition slightly affected SIN1 expression in thyroid cancer cells." (PMID 36471438, 2022).
acromegaly (1 paper, 2021). Acromegaly is an acquired disorder related to excessive production of growth hormone (GH) and characterized by progressive somatic disfigurement (mainly involving the face and extremities) and systemic manifestations. "For preoperative acromegaly, SOCS2, cullin-5 and Rbx-2 showed high diagnostic accuracies with 0.91, 0.96 and 0.96, respectively." (PMID 33671326, 2021). "The significant elevations of SOCS2, cullin-5 and Rbx-2 in the preoperative acromegaly group show that these proteins might be candidates for disease detection." (PMID 33671326, 2021). "Preoperative acromegaly patients were characterized by higher levels of SOCS2 (1128.8 ± 471.0 pg/mL, p = 0.003), cullin-5 (60.99 ± 30.29 ng/mL, p = 0.001) and Rbx-2 (56.4 ± 31.1 pg/mL, p = 0.0002) compared to controls." (PMID 33671326, 2021). "Unfortunately, comparable statistics of IGF-1 for acromegaly have not been found, but our results suggest an excellent diagnostic performance using the three ECS-complex proteins SOCS2, cullin-5 and Rbx-2 in conjunction." (PMID 33671326, 2021).
adrenocortical carcinoma (1 paper, 2021). "The poor OS for ACC (adrenocortical carcinoma) was linked to high CUL5 expression (P = 0.0031)." (PMID 34415831, 2021).
allergic disease (1 paper, 2022). An immune response that occurs following re-exposure to an innocuous antigen, and that requires the presence of existing antibodies against that antigen. "Here the authors show that an E3 ubiquitin ligase Cul5 alters TH2 and TH9 development and absence of Cul5 in T cells results in higher levels of allergy-associated IL-4 and IL-9 secreting T cells." (PMID 35589717, 2022). "However, two previous studies support a function for Cul5 and CIS in allergic disease." (PMID 35589717, 2022). "However, additional studies are needed to determine how Cul5 and/or CIS regulate human T cells to prevent allergic disease and whether these factors might be targeted for therapeutic effect." (PMID 35589717, 2022).
ataxia telangiectasia (1 paper, 2013). Ataxia-telangiectasia is the association of severe combined immunodeficiency (affecting mainly the humoral immune response) with progressive cerebellar ataxia. "This region contains the NPAT and ATM genes associated with ataxia telangiectasia characterized by language impairment; the CUL5 (culin 5) gene in the same region may modulate the neuronal migration process related to language functions." (PMID 23977206, 2013).
atopic asthma (1 paper, 2022). An asthma that is characterized by symptoms that are triggered by an allergic reaction caused by inhaled allergens such as dust mite allergen, pet dander, pollen and mold. "Mice lacking Cul5 in T cells develop Th2 and Th9 inflammation and show pathophysiological features of atopic asthma." (PMID 35589717, 2022).
autoimmune disease (1 paper, 2025). A disorder resulting from loss of function or tissue destruction of an organ or multiple organs, arising from humoral or cellular immune responses of the individual to their own tissue constituents. "The findings presented here represent an important first step in understanding the role of CUL5 in neuroinflammation and establishing a foundation for future research into its therapeutic potential in MS and other autoimmune diseases." (PMID 40842987, 2025).
Autoimmunity (1 paper, 2025). The occurrence of an immune reaction against the organism's own cells or tissues. "We identified CUL5 as a primary molecular target of NAEi therapy and demonstrated that blocking CRL neddylation using NAEi can restore proper Treg function in human Treg assays in vitro and in animal models of autoimmunity in vivo." (PMID 40852720, 2025). "Therapeutic strategies aimed at stabilizing IL-2R signaling, via GRAIL modulation, inhibition of premature CUL5 neddylation, or DEPTOR preservation, may represent promising interventions to restore immune tolerance in autoimmunity." (PMID 40852720, 2025).
bladder cancer (1 paper, 2026). "We found that CUL5 knockout promoted the sensitivity of bladder cancer cells to CD8+ T cell-mediated killing both in vivo and in vitro." (PMID 41662369, 2026). "Here, we performed a whole genome CRISPR-Cas9 knockout screen under CD8+ T cells pressure and identified the E3 ubiquitin ligase CUL5 as an essential factor required for escaping CD8+ T cells killing in bladder cancer cells." (PMID 41662369, 2026). "Mechanistically, CUL5 loss reduced the ubiquitination of PTBP1, which regulated alternative splicing of RUBCN pre-mRNA and led to an increase in the levels of the RUBCN-S isoform, thereby preventing immune evasion of bladder cancer cells by inhibiting autophagy." (PMID 41662369, 2026).
Cockayne syndrome (1 paper, 2017). A multisystem condition characterized by short stature, a characteristic facial appearance, premature aging, photosensitivity, progressive neurological dysfunction, and intellectual deficit. "In this study, we demonstrate (i) that Elongin A and the ubiquitin ligase subunit CUL5 associate in cells with the Cockayne syndrome B (CSB) protein and (ii) that this interaction is also induced by DNA-damaging agents and α-amanitin." (PMID 28292928, 2017).
cyst (1 paper, 2010). A sac-like closed membranous structure that may be empty or contain fluid or amorphous material. "An alternative explanation, that membrane reductions causing fusions of cyst cells underlie this phenotype is unlikely in this case, as we only extremely rarely observed multinuclear cells in cul-5 mutant egg chambers." (PMID 20140218, 2010). "We provide evidence that Cul-5 CRLs are involved in Drosophila follicular morphogenesis, in the regulation of germ line cyst divisions and in germ line maintenance, and that some of these Cul-5 CRLs most likely include Gus." (PMID 20140218, 2010). "Therefore, Cul-5 and Encore have in common that they act in ubiquitin-dependent pathways that affect both germ line cyst divisions as well as morphogenesis of the follicular epithelium." (PMID 20140218, 2010). "Also, the follicular epithelium that normally encapsulates single germ line cysts develops aberrantly in cul-5 mutant, leading to defects in cyst formation." (PMID 20140218, 2010).
experimental autoimmune encephalomyelitis (1 paper, 2025). An autoimmune demyelinating disease of the central nervous system that is produced experimentally in animals by the injection of homogenized brain or spinal cord in Freund's adjuvant. "Here we show that loss of Cul5 in myeloid cells resulted in reduced neuroinflammation and attenuated progression of Experimental Autoimmune Encephalomyelitis (EAE)." (PMID 40842987, 2025).
glioma (1 paper, 2020). A benign or malignant brain and spinal cord tumor that arises from glial cells (astrocytes, oligodendrocytes, ependymal cells). "The expression levels of CUL5 did not correlate with glioma WHO grades." (PMID 32931454, 2020).
head and neck squamous cell carcinoma (1 paper, 2021). A squamous cell carcinoma that arises from any of the following anatomic sites: lip and oral cavity, nasal cavity, paranasal sinuses, pharynx, larynx, and salivary glands. "CUL5 expression is associated with CD8 + T-cell infiltration levels in uveal melanomas and head and neck squamous cell carcinomas, and we observed a positive relationship between CUL5 and Tcm (T central memory) cells, and a negative relationship between T helper (Th) cells and pDC (plasmacytoid DC)." (PMID 34415831, 2021).
hepatocellular carcinoma (1 paper, 2016). A malignant tumor that arises from hepatocytes. "miR-7, which upregulates Cul5 expression, is downregulated in hepatocellular carcinoma (HCC) tissues compared with adjacent non-tumor tissue." (PMID 27030794, 2016).
Hyperglycemia (1 paper, 2024). An increased concentration of glucose in the blood. "In contrast to the results from CUL1 knockdown, knockdown of CUL3 or CUL5 did not improve the hyperglycemia of HSD flies." (PMID 38212312, 2024).
influenza (1 paper, 2024). An acute viral infection of the respiratory tract, occurring in isolated cases, in epidemics, or in pandemics; it is caused by serologically different strains of viruses (influenzaviruses) designated A, B, and C, has a 3-day incubation period, and usually lasts for 3 to 10 days. "As influenza administration combined with the HDM challenges (HDM + PR8) significantly increased neutrophilic inflammation compared to the HDM group, we assessed the effect of CUL5 on neutrophilic inflammation in the airways." (PMID 38177117, 2024).
multiple myeloma (1 paper, 2018). "Consequently, CUL5 may be an important part of the mechanism for thalidomide-dependent inhibition of cellular proliferation, as well as a novel biomarker for predicting a response to thalidomide for the treatment of disorders such as multiple myeloma and HIV infection." (PMID 29746508, 2018).
myeloproliferative neoplasm (1 paper, 2025). A clonal hematopoietic stem cell disorder, characterized by proliferation in the bone marrow of one or more of the myeloid (i.e., granulocytic, erythroid, megakaryocytic, and mast cell) lineages. "Our research demonstrates that CUL5 binds 9 different substrate receptors in cultured HSPCs, broadening the repertoire of PROTAC designs that are feasible and relevant for HSCs and myeloproliferative neoplasm." (PMID 40569692, 2025).
osteosarcoma (1 paper, 2017). A usually aggressive malignant bone-forming mesenchymal neoplasm, predominantly affecting adolescents and young adults. "Among the other six Cullins, only CUL4A was slightly overexpressed (~1.4–1.7-fold induction) in osteosarcoma cells, but not the other five Cullins, including CUL1, CUL2, CUL3, CUL5 and CUL7." (PMID 28446751, 2017).
Pan (1 paper, 2021). "Pan-cancer results on whole tumors were not obtained through our literature search of other publications on CUL5." (PMID 34415831, 2021).
renal carcinoma (1 paper, 2019). A carcinoma arising from the epithelium of the renal parenchyma or the renal pelvis. "Since the metastatic ACHN cells present low CUL5 mRNA levels together with a high percentage of centriole overduplication, compared to normal hRECs, CUL5 may be an important factor for the progression of renal carcinoma." (PMID 30631037, 2019).
serous endometrial adenocarcinoma (1 paper, 2021). "While previous research has suggested that CUL5 expression decreases in serous endometrial adenocarcinoma cases, but we could not confirm a relationship between CUL5 expression in TCGA-OV and the survival prognosis." (PMID 34415831, 2021).
Splenomegaly (1 paper, 2025). Abnormal increased size of the spleen. "Here we report that mice lacking CUL5 in hematopoietic cells (Cul5Vav-Cre) have increased numbers of hematopoietic stem and progenitor cells (HSPCs), splenomegaly, and extramedullary hematopoiesis." (PMID 40569692, 2025).